INS (insulin)
Diseases named in the same sentence as INS in open-access papers (continued):
Sharing a sentence is not in itself a finding about the gene and the disease.
gestational diabetes (continued). "Only in fetal vessels from patients with insulin-treated gestational diabetes were we able to detect an endothelial dysfunction and a reduced fetal insulin conversion." (PMID 39384641, 2025). "A study involving 84 patients with gestational diabetes showed that, compared to insulin therapy alone, the combination of insulin and astragalus significantly reduced levels of total cholesterol, triglycerides, and low-density lipoproteins." (PMID 40276608, 2025). "In women with gestational diabetes with a BMI ≥ 25 kg m−2, provision of an energy-restricted diet reduced the requirement for long-acting insulin." (PMID 39972237, 2025). "Comparison of fetal pulmonary artery parameters between diet‐regulated and insulin‐regulated gestational diabetes mellitus cases." (PMID 40635636, 2025). "The analysis of the area under the curve revealed a significantly increased area in patients with insulin-treated gestational diabetes compared to the control group." (PMID 39384641, 2025). "Based on these therapeutic options, women with GDM have usually insulin-treated gestational diabetes (iGDM) or diet-controlled gestational diabetes (dGDM)." (PMID 39384641, 2025). "With the discontinuation of insulin detemir (previously the only FDA-approved insulin for pregnancy), IG and insulin degludec have emerged as the recommended alternative therapies for gestational diabetes management." (PMID 40997126, 2025). "Gestational diabetes mellitus (GDM) poses a significant challenge due to its variable insulin requirements and impact on pregnancy outcomes." (PMID 41623786, 2025). "Insulin is a first-line pharmacological treatment for gestational diabetes mellitus (GDM) when lifestyle modifications such as diet and exercise fail to maintain optimal blood glucose levels." (PMID 40369565, 2025). "The study of gestational diabetes evaluated the safety and efficacy of Humalog Mix 50/50TM administered as 3 injections daily, compared to Humalog Plus Humulin N insulin administered as 6 separate injections daily for women with GDM." (PMID 39889198, 2025). "Evidence consistently links Mediterranean-style eating to improved metabolic health, insulin sensitivity, IVF success, lower gestational diabetes risk, and favorable neonatal outcomes." (PMID 41305556, 2025). "Increasing dietary fibre was associated with lower fasting and 2‐h postprandial blood glucose values and reduced requirement to introduce insulin therapy in women with gestational diabetes." (PMID 39473074, 2025). "Background/Objectives: Maternal amino acid intake and its biological value may influence glucose regulation and insulin sensitivity, impacting the risk of developing gestational diabetes mellitus (GDM)." (PMID 39796608, 2025). "Gestational diabetes typically occurs in the second half of pregnancy when the demand for insulin increases, and it often resolves within a few days after parturition." (PMID 40005887, 2025). "Pregnancy is associated with metabolic changes that involve the increased release of insulin counter-regulatory hormones, leading to insulin resistance and glucose intolerance, which can contribute to the development of Gestational Diabetes Mellitus (GDM)." (PMID 41295285, 2025). "Energy restriction in pregnancy was safe and reduced the requirement to start long-acting insulin in gestational diabetes." (PMID 39972237, 2025). "This aligns with previous research showing that PLP deficiency impairs insulin secretion in rats, whereas PLP supplementation helps prevent diabetic complications and improves outcomes in gestational diabetes." (PMID 40078416, 2025). "Gestational diabetes mellitus (GDM) is a condition in which a hormone made by the placenta prevents the body from using insulin effectively." (PMID 40410732, 2025).
gestational diabetes (continued). "Studies have shown that the risk of obesity, metabolic syndrome, type 2 diabetes, and impaired insulin sensitivity in the offspring of mothers with GDM (gestational diabetes mellitus) is two to eight times higher than in the offspring of mothers without GDM." (PMID 40217843, 2025). "In women with PCOS and gestational diabetes, magnesium combined with vitamin E significantly reduced fasting insulin level (−2.93μIU/mL) and HOMA-IR index (−0.78), while improving insulin sensitivity index (QUICKI+0.01)." (PMID 40959697, 2025). "Increasing dietary fibre by 9.3 g decreases fasting and 2‐h postprandial glucose and reduces the likelihood of requiring insulin therapy in women with gestational diabetes." (PMID 39473074, 2025). "A Chinese study involving 398 multiparous pregnant women found that high TAU levels in women were associated with a reduced risk of gestational diabetes mellitus as well as with an increase in HOMA-β index, suggesting an improvement in insulin secretion." (PMID 40869416, 2025). "These women require more intensive management than those with gestational diabetes due to the higher likelihood of requiring insulin therapy, developing preeclampsia, and delivering large-for-gestational-age (LGA) infants." (PMID 40650275, 2025). "The patient was born at 40 weeks gestation after a pregnancy complicated by maternal gestational diabetes treated with insulin." (PMID 38535121, 2024). "In the overweight/obese reference group, the use of insulin was reported for the treatment of gestational diabetes in two cases (1%)." (PMID 38663923, 2024). "Another study including women with pre-gestational diabetes reported that treatment with metformin plus insulin resulted in fewer cesarean deliveries compared to metformin alone or insulin alone (52.2%, 81.2%, and 82%, respectively, p < 0.01)." (PMID 37798604, 2024). "Glibenclamide, a sulfonylurea derivative, is used primarily as an oral antidiabetic agent in patients with DM type 2 and gestational diabetes due to its ability to stimulate insulin secretion in pancreatic β-cells." (PMID 38255742, 2024). "During normal pregnancy, β-cells undergo hyperplasia in order to meet the metabolic demands of pregnancy, while during gestational diabetes, β-cells fail to compensate for the demands of pregnancy on a background chronic insulin resistance." (PMID 38029302, 2024). "There is a potential viability of using metformin as an alternative compared to insulin alone in the treatment of Gestational Diabetes Mellitus." (PMID 39669300, 2024). "Our study partially corroborates findings from research on women with gestational diabetes, where co-supplementation with vitamin D and probiotics led to significant reductions in fasting glucose and serum insulin levels, thereby enhancing insulin sensitivity." (PMID 38732578, 2024). "Comparison of FBG, RBG, and Insulin levels in pregnant women with gestational diabetes mellitus (GDM) according to ethnicity of the patients." (PMID 39035597, 2024). "Standard therapy for gestational diabetes requiring insulin therapy has shown better maternal and newborn outcomes compared to diet, oral anti-diabetic drugs, or insulin analogues, with a lower incidence of macrosomia." (PMID 39767708, 2024). "Gestational diabetes mellitus (GDM) is a common pregnancy complication that is associated with impaired glucose metabolism and disturbance of insulin sensitivity, and it can cause serious health problems and, therefore, has significant implications for both maternal and fetal health." (PMID 39795898, 2024). "Adequate vitamin D levels may thus play a critical role in preserving glucose balance and insulin sensitivity throughout pregnancy, potentially lowering the likelihood of gestational diabetes mellitus (GDM) and its associated complications." (PMID 39203767, 2024).
gestational diabetes (continued). "Women with insulin-treated pre-gestational diabetes mellitus had the poorest outcomes regarding breastfeeding rates, both in intention to breastfeed and at hospital discharge." (PMID 38338291, 2024). "Still, it was found to be deranged at 28 weeks, indicating the development of gestational diabetes mellitus (GDM) for which the patient received insulin." (PMID 39224726, 2024). "Microbiota-targeted interventions are very helpful for maternal glycaemic control, insulin metabolism, and balancing inflammatory and oxidative stress markers in gestational diabetes." (PMID 39269153, 2024). "We have demonstrated, through this study, the potential viability of using metformin as an alternative compared to insulin therapy in the treatment of Gestational Diabetes Mellitus." (PMID 39669300, 2024). "Diosgenin decreases gestational diabetes in db/ + pregnant mice, by improvements in glucose and insulin resistance, a decline in fasting blood glucose and insulin levels, and an increase in hepatic glycogen content." (PMID 38371502, 2024). "Four (5.1%) of the mothers in the study have gestational diabetes; two were managed with diet, and the other four required insulin therapy." (PMID 39420012, 2024). "Gestational diabetes mellitus (GDM) is defined as a the condition in which insulin cannot be utilized efficiently by the body because of a hormone secreted by the placenta." (PMID 39035597, 2024). "Her mother suffered from gestational diabetes mellitus and needed an insulin injection at 7 months of gestation." (PMID 38591167, 2024). "As one of the most serious and prevalent pregnancy complications, gestational diabetes mellitus (GDM) is induced by inadequate insulin production or signaling during pregnancy." (PMID 39885928, 2024). "In cases of severe gestational diabetes (defined as fasting glucose > 100 mg/dL, 1-h postprandial glucose > 140 mg/dL, or fetal abdominal circumference > the 90th percentile), insulin therapy was initiated promptly." (PMID 39683486, 2024). "The GWG related CpG site was associated with levels of C-peptide, insulin, HOMA-IR and gestational diabetes mellitus using WHO 2013 criteria." (PMID 38219005, 2024). "This increased risk is attributed to factors such as postpartum hemorrhage, gestational diabetes, and gestational hypertension due to reduced insulin sensitivity, vascular endothelial dysfunction, and decreased oxytocin receptors." (PMID 39440038, 2024). "The pathophysiology of gestational diabetes mellitus is thought to relate to an ineffective beta cell response to compensate for the increasing insulin resistance observed as gestation advances." (PMID 38225599, 2024). "Similar proportions of women with gestational diabetes mellitus complied with dietary recommendations (group 2: 81%, group 3: 86%) and were treated with insulin (group 2: 19%, group 3: 21%)." (PMID 39519317, 2024). "The time to stop insulin treatment in a case series of gestational diabetes that achieved diabetic remission after pregnancy termination ranged from 7 to 21 days (median: 9)." (PMID 38539988, 2024). "Another study conducted in Al Madinah revealed that 22.5% of the participants were aware that insulin is a treatment option for gestational diabetes." (PMID 38420077, 2024). "This review investigated the efficacy of probiotics and/or synbiotics in gestational diabetes mellitus treatment by targeting insulin resistance, lipid metabolism, and anti-inflammatory effects in an updated trial." (PMID 38322777, 2024). "Women with pregestational diabetes or those requiring insulin treatment had a higher propensity for preterm delivery compared to those with gestational diabetes managed through diet control alone." (PMID 38999295, 2024). "Several studies have indicated that mothers with gestational diabetes mellitus (GDM)-associated altered glucose metabolism and insulin resistance conditions lead to neurodevelopmental disorders such as ASD." (PMID 39758437, 2024).
gestational diabetes (continued). "The placenta is also implicated in gestational diabetes mellitus (GDM), a condition in which pregnancy and pregnancy-related hormones limit efficient insulin production." (PMID 38505610, 2024). "Serial ultrasounds are used in women with gestational diabetes where insulin treatment is titrated according to the acceleration of the foetal abdominal circumference." (PMID 38933924, 2024). "Gestational diabetes is a type of glucose intolerance that develops during pregnancy as a result of insufficient insulin supply to meet tissue demands for standard blood glucose regulation." (PMID 38371502, 2024). "Administration of high doses of vitamin D has been observed to increase insulin sensitivity and decrease insulin levels in women with gestational diabetes." (PMID 38698459, 2024). "The main results in this study were that despite normoglycaemia, South Asian women displayed higher adipose tissue insulin resistance than Nordic women when examined 1–3 years after gestational diabetes mellitus." (PMID 38786765, 2024). "Numerous studies describe outcomes where women were managed according to local gestational diabetes guidelines and there is a paucity of literature comparing management of insulin and SU in this population." (PMID 38933924, 2024). "During the late trimester of pregnancy, a pregnant person with gestational diabetes exhibits low glucose uptake rates, decreased insulin secretion, and high insulin resistance." (PMID 39885928, 2024). "The primary approach to managing gestational diabetes is a combination of dietary modifications, structured physical activity, regular monitoring of glycemic levels, and, if necessary, insulin therapy." (PMID 39683486, 2024). "This study shows that less than half of the participants (44.6%) knew that insulin is one of the treatments available fore gestational diabetes." (PMID 38420077, 2024). "The studies conducted in singleton pregnancies align with our own findings in twin pregnancy and support the notion that fasting glucose levels are a strong predictor of the need for antenatal insulin treatment in cases of gestational diabetes." (PMID 39346677, 2024). "When insulin secretion is unable to fully counteract insulin resistance, blood glucose levels increase, resulting in the development of gestational diabetes mellitus (GDM)." (PMID 39876919, 2024). "Although both are characterized by reduced insulin sensitivity, gestational diabetes is considered as a separate condition." (PMID 37651381, 2023). "Two follow-up studies of children aged 2 to 9 years whose mothers had gestational diabetes showed that several growth parameters tended to be larger in metformin-exposed offspring than in offspring exposed to insulin." (PMID 36593391, 2023). "Further studies have reported a significant relationship between fasting plasma glucose levels and the need for insulin therapy for treatment of gestational diabetes mellitus." (PMID 37959321, 2023). "We developed an easily applicable tool to accurately predict insulin dependency in gestational diabetes." (PMID 38002781, 2023). "In support of our results, a previous study reported a significant reduction in the postprandial blood sugar (PPBS) level and insulin dose among pregnant women with gestational diabetes mellitus (GDM) after receiving maternal nursing health education sessions." (PMID 37211603, 2023). "It was determined that 62% (n = 62) of the pregnant women with gestational diabetes were treated with diet, 36% (n = 36) with insulin therapy, and 2% (n = 2) with both diet and exercise therapy." (PMID 36977403, 2023). "The objective of this retrospective study was to compare glycemic control, pregnancy outcomes, and neonatal outcomes in women with gestational diabetes mellitus (GDM) treated with (a) insulin detemir and (b) insulin neutral protamine Hagedorn (NPH)." (PMID 37775682, 2023).
gestational diabetes (continued). "The insulin resistance of pregnancy is exacerbated by maternal obesity, excessive gestational weight gain, and gestational diabetes, resulting in even lower maternal levels of adiponectin and higher levels of insulin, leptin, and IGF-1." (PMID 37764824, 2023). "Decreased percentages of CD14+ CMs and increased abundances of IMs have also been observed in gestational diabetes mellitus, in which a hormone (human chorionic gonadotropin) made by the placenta prevents the body from using insulin effectively." (PMID 36921085, 2023). "Premature adrenarche, PCOS, and gestational diabetes can occur due to shifting to androgenic gonadal steroid levels and reduced insulin sensitivity." (PMID 36909346, 2023). "The role of vitamin D has also been considered with regard to disorders connected to the pregnancy of gestational diabetes; a relationship between polymorphic forms of vitamin D and impaired glucose tolerance and insulin release has been identified." (PMID 37371857, 2023). "Several treatment strategies have been proposed, with insulin considered the gold standard for managing gestational diabetes." (PMID 37469977, 2023). "Apart from one study looking at the effect of chilli on glucose and insulin in pregnant women with gestational diabetes, all the included studies were in healthy individuals." (PMID 38068725, 2023). "When a pregnant woman’s body is incapable of acclimatize to her new environment and her endocrine system becomes unable to create adequate insulin, gestational diabetes mellitus develops." (PMID 37109521, 2023). "Monitoring insulin levels, therefore, can be crucial in the early detection and management of gestational diabetes." (PMID 37374343, 2023). "A meta-analysis of four RCTs (198 participants) found that magnesium supplementation in gestational diabetes mellitus patients significantly improved glycemic control and reduced insulin levels, positively impacting insulin sensitivity and oxidative stress." (PMID 38074055, 2023). "Raised maternal BMI increases rates of gestational diabetes mellitus (GDM), which is a transient state of relative insulin resistance during pregnancy that increases LGA risk." (PMID 36809384, 2023). "In line with this, there are other studies investigating detemir versus NPH in pregnancies with pregestational and gestational diabetes, possibly due to the intensive insulin regimen including short-acting insulins." (PMID 37775682, 2023). "Pregnant people treated for gestational diabetes were assigned higher prenatal care costs to reflect the costs of additional office visits, medical nutrition therapy, and in some cases, insulin treatment." (PMID 36580414, 2022). "Gestational diabetes mellitus (GDM) is characterized by insufficient insulin secretion and impaired glucose intolerance during pregnancy." (PMID 36936475, 2022). "In diabetic mothers, exercise-induced apelin has preventive effects on gestational diabetes by reducing insulin and glucose in maternal circulation, reducing weight, reducing insulin resistance, and improving glucose tolerance in skeletal muscles." (PMID 36093083, 2022). "Exosomes are released from decreased insulin sensitivity and glucose uptake in skeletal muscles, contributing to the pathophysiology of gestational diabetes mellitus (GDM)." (PMID 35681164, 2022). "Maternal gestational diabetes exposes the fetus to higher concentrations of glucose than normal, which forces the fetus to increase its own insulin production." (PMID 35626396, 2022). "The policy was also associated with a 10.4-percentage-point (95% CI, 5.3-15.5 percentage points) increase in insulin use during pregnancy among all patients with gestational diabetes." (PMID 35486400, 2022). "It is important to consider that inadequate management of gestational diabetes can lead to various complications, including increased likelihood of a large-for-gestational-age newborn, cesarean section, increased fetal insulin levels, and neonatal fat levels." (PMID 35310000, 2022).